CRP (C-reactive protein)
Diseases named in the same sentence as CRP in open-access papers (continued):
Sharing a sentence is not in itself a finding about the gene and the disease.
vitamin D deficiency (continued). "However, this does not apply to general population cohorts like the UK Biobank, in which the association of vitamin D deficiency and CRP is confounded by body weight." (PMID 37340242, 2023). "The observed association between 25(OH)D and CRP is likely to be caused by vitamin D deficiency." (PMID 35579027, 2023). "Moreover, NDMM patients who exhibited a vitamin D deficiency status below 50 nmol/L (20 ng/mL) demonstrated increased mean values for serum C-reactive protein (CRP) and creatinine, as well as decreased serum albumin levels." (PMID 37513645, 2023). "The finding that vitamin D deficiency was lower in infliximab-treated patients is likely to be explained by more active disease at baseline evidenced by a higher serum CRP and fecal calprotectin observed in infliximab- compared to adalimumab-treated patients in this real-world study." (PMID 37265586, 2023). "However, when using clinical classification to categorize into deficiency (<20 ng/mL), insufficiency (20–30 ng/mL), and sufficiency (>30 ng/mL), we found that vitamin D deficiency is strongly associated with higher levels of CRP." (PMID 35057447, 2022). "Thus, the baseline CRP was 79.7 [32.5; 146.7] mg/L in patients with a vitamin D deficiency/insufficiency and 28.3 [7.6; 62.5] mg/L in patients with a normal vitamin D status, p < 0.001." (PMID 35337103, 2022). "Subjects with vitamin D deficiency and CRP levels ≥0.2 mg/dL represent a higher chance to have CVD." (PMID 31020672, 2019). "We hypothesized that vitamin D deficiency and CRP in these patients might be associated with an increased 1-year mortality." (PMID 26833068, 2016). "In addition, vitamin D deficiency is related to novel cardiovascular risk factors such as C-Reactive Protein and pro-inflammatory cytokines." (PMID 26437924, 2015). "Inflammatory cytokines (IL-6, IL-10, CRP, etc) are elevated in Vitamin D deficiency." (PMID 27417476, 2014). "Thus, only CRP showed a significant difference between the groups, suggesting that patients with vitamin D deficiency experience a more intense inflammatory response, which may contribute to the severity of the infection." (PMID 40217860, 2025). "Thus, elucidating the effect of vitamin D deficiency and hs-CRP levels on mortality could be beneficial in preventing premature death and improving life expectancy." (PMID 38302956, 2024). "Vitamin D deficiency is associated with increased inflammatory markers in diabetics including C-reactive protein (CRP), monocyte toll-like receptor 2 (TLR-2), TLR-4, and nuclear factor-κB (NFκB) expression which might predict increased risk of microvascular complications." (PMID 32467811, 2020). "If the inverse relation between vitamin D and CRP in neonates with low vitamin D levels in this study is causality, the findings raised a possibility of protection against excessive inflammatory response in the fetus through vitamin D supplementation among pregnant women with vitamin D deficiency." (PMID 26569292, 2015). "In summary, CKD, the increase of FGF‐23, and vitamin D deficiency are all associated with the occurrence of SHPT, and they are all associated with CRP." (PMID 37102663, 2023). "Multivariate model assessing mortality adjusted for vitamin D deficiency, ICU admission, DVT or PE, length of stay, peak D-dimer, peak CRP, peak fibrinogen, and peak LDH." (PMID 37575807, 2023). "Zhou and Hypponen, observed an association between 25(OH)D and C-reactive protein (CRP) levels, and they attributed the cause to vitamin D deficiency." (PMID 37592222, 2023). "We identified a positive effect of supplementation on perioperative 25OHD levels with lower rates of post-operative vitamin D insufficiency and reduced early post-operative CRP." (PMID 37063332, 2023). "Vitamin D insufficiency correlated to higher s IgE and Hs-CRP levels which are markers of eosinophilic inflammation." (PMID 37519504, 2023).
vitamin D deficiency (continued). "High dose pre-operative vitamin D supplementation is associated with higher perioperative 25OHD levels, lower rates of vitamin D insufficiency and reduced early post-operative CRP." (PMID 37063332, 2023). "On the contrary, a similar trial with mildly-moderately affected patients with vitamin D insufficiency reached statistical significance in all (N/L ratio, CRP, LDH, IL6, Ferritin) measured markers." (PMID 35330419, 2022). "Low levels of HDL and high levels of ESR, hs-CRP, SAA, and PLT were considered independent risk factors for mild vitamin D deficiency." (PMID 35495921, 2022). "Other studies have supported the anti-inflammatory effects of vitamin D. A four-week administration of cholecalciferol significantly lowered the hs-CRP levels in older females with vitamin D insufficiency." (PMID 33624705, 2021). "Pregnant women with non-vitamin D deficiency have lower TC, TG, HDL-C, LDL-C, and hs-CRP levels compared with those deficient." (PMID 32684941, 2020). "Increased BMI and WHR, high levels of fasting insulin, HOMA-IR, total cholesterol, LDL-C and hs-CRP were regarded as risk factors, but high level of HDL-C was considered to be protective factor of vitamin D deficiency in PCOS women." (PMID 32296394, 2020). "In subjects with high CRP, the OR of having CVD was 2.43 (95% CI = 1.23‐4.82, P = .0110) in individuals who also exhibited severe vitamin D deficiency compared with those with normal vitamin D levels." (PMID 31020672, 2019). "On the contrary, vitamin D deficiency is associated with high level of inflammatory factors such as IL-6, TNF-α, and C-reactive protein (CRP)." (PMID 25741510, 2015). "Third, long-term vitamin D insufficiency and deficiency cause secondary hyperparathyroidism, which in turn may mediate many of the detrimental CV effects including increasing systemic inflammation, as indicated by increased levels of C-reactive protein, homocysteine, and interleukin-10." (PMID 25528383, 2014). "Elevated CRP levels were related to low vitamin D levels, with a higher probability of slow walking speed, which was attenuated when vitamin D deficiency was absent, although the relevant factor inducing slow gait was CRP." (PMID 38338653, 2024). "This study showed that vitamin D deficiency is associated with disadvantageous levels of blood cell count-based but not CRP-based biomarkers of SIR." (PMID 37340242, 2023). "Vitamin D deficiency was associated with disadvantageous levels of all blood cell count-based biomarkers, but not with C-reactive protein (CRP)-based biomarkers after adjustment for body weight." (PMID 37340242, 2023). "In Model 1–3, which did not adjust for body weight, we observed that both vitamin D deficiency and insufficiency were consistently associated with the disadvantageous level of all CRP-based biomarkers of SIR." (PMID 37340242, 2023). "Previous studies reported that vitamin D deficiency was associated with a decrease in the concentration of vitamin D receptors (VDR) and that the level of VDR was negatively correlated with SOFA score and lactate and C-reactive protein levels." (PMID 37892385, 2023). "With data from almost 400,000 individuals from the UK Biobank, this study showed strong cross-sectional associations of vitamin D deficiency with disadvantageous levels of all blood cell count-based biomarkers of SIR but not with the CRP-based biomarkers." (PMID 37340242, 2023). "Vitamin D deficiency was found in 67.2% and was independent of sex, disease manifestation, and CRP, ESR, ALP, or PO4 levels." (PMID 35458206, 2022). "The inflammation markers, including interleukin (IL)−1 beta, IL-6, tumor necrosis factor (TNF)-alpha, and, high-sensitivity C-reactive protein (hs-CRP) were also not significantly different between the study patients with and without vitamin D deficiency." (PMID 32371900, 2020).
vitamin D deficiency (continued). "However, the correlation of vitamin D deficiency with ICU outcomes decreased after adjusting for age, serum calcium and phosphor, BUN, Cr, CRP, Hb, and Alb." (PMID 31531086, 2019). "Concomitant medical therapies (e.g. corticosteroids, thiopurines or biologics including TNF inhibitors) and biomarkers of inflammation (concentrations of leukocytes, platelets or C-reactive protein) did not correlate with the diagnosis of vitamin D deficiency." (PMID 31120977, 2019). "A clinical trial showed that 4 weeks supplementation with 200,000 IU of vitamin D3 administered as a single dose improved the serum 25(OH)D and TAC levels and significantly lower the us-CRP (Ultra-Sensitive CRP) levels in old females with vitamin D insufficiency." (PMID 31350967, 2019). "A recent Mendelian randomization study found no causal relationship between vitamin D and CRP, which suggests that it is unlikely that vitamin D deficiency directly contributes to increased inflammation or vice versa." (PMID 28241878, 2017). "The available data suggest that poor nutritional status and vitamin D deficiency might be associated with increased levels of proinflammatory factors, such as TNF-α, IL-6, and CRP." (PMID 27274758, 2016). "Severity of injury, extent of inflammation (elevated C-reactive protein concentration), or hospital admission during the winter season did not significantly influence the prevalence of vitamin D deficiency." (PMID 27833924, 2016). "In other words, we did not observe an association between vitamin D deficiency and CRP levels anyway." (PMID 23878538, 2013). "Furthermore, the Ob group with vitamin D deficiency also showed higher levels of C-reactive protein (CRP) vs the NON-OB one (p < 0.05), indicative of low-grade systemic inflammation." (PMID 40261445, 2025). "Furthermore, the data from logistic regression model of risk factors for vitamin D deficiency revealed that increased BMI and WHR, high levels of fasting insulin, HOMA-IR, total cholesterol, LDL-C, and hs-CRP were regarded as risk factors of vitamin D deficiency in PCOS women." (PMID 32296394, 2020). "Inclusion criteria were absence of infection validated by normal body temperature, blood leucocyte count and C-reactive protein (CRP) as well as absence of vitamin D deficiency with serum levels of > 30 ng/ml and disturbances in the calcium phosphate metabolism." (PMID 29931529, 2019). "Indeed, patients with versus without severe vitamin D deficiency (25(OH)D3 serum concentration) had significantly higher serum concentrations of CRP (0.85 mg/dL (SD = 1.3) versus 0.43 mg/dL (SD = 0.7), P = 0.007)." (PMID 30408125, 2018). "Furthermore, an important finding in this study, compared to other up‐to‐date research, is that vitamin D deficiency was strongly associated with the presence of albuminuria in T2D patients, independent of basic inflammatory markers (hs‐CRP and TNF‐α) and the GFR." (PMID 40804707, 2025). "The evidence from this study suggested that there is a strong association between vitamin D deficiency and albuminuria in T2D patients, irrespective of both the eGFR and inflammatory marker levels, such as the serum TNF‐α and hs‐CRP levels." (PMID 40804707, 2025). "In a previous study, the effect of vitamin D3 supplementation and the influence of Bsm1 in elderly women with vitamin D insufficiency was that the treatment increased the vitamin levels and reduced PTH, CRP, and 1-acid glycoprotein in patients with BB and Bb genotypes but not those with bb." (PMID 39335504, 2024). "Based on the weak and inconsistent correlations between CRP or AGP and 25(OH)D, there is no rationale to adjust for these inflammation biomarkers when estimating population prevalence of vitamin D deficiency in PSC or FRA." (PMID 36789936, 2023). "We did not observe any difference in the clinical parameters, pulmonary function, inflammatory markers (ESR, CRP), and quality of life in subjects with CPA with or without vitamin D deficiency." (PMID 33019741, 2020).
vitamin D deficiency (continued). "We found that the inflammatory markers, comprising hs-CRP and inflammatory cytokines (IL-1 beta, IL-6, and TNF-alpha), were similar between hemodialysis patients with and without vitamin D deficiency." (PMID 32371900, 2020). "In patients with the optimal vitamin D levels (30–100 ng/mL), CRP, IL-6 and erythrocyte sedimentation rate (ESR) were 8.21±0.57, 12.08±0.55 pg/mL and 18.29±4.21 mm/hour, respectively; in other words, they were 19.4%, 27.2% and 52% lower than in patients with vitamin D insufficiency (p<0.05)." (PMID 37558268, 2023). "Of note, serum levels of C-reactive protein, IL-6 and soluble CD14 were significantly higher in patients with versus without severe vitamin D deficiency, and serum levels of soluble CD14 levels declined in patients with de novo supplementation of vitamin D (median 2.15 vs. 1.87 ng/mL, P = 0.002)." (PMID 30408125, 2018). "Furthermore, patients with vitamin D deficiency had lower HDL (41 mg/dL, IQR 30–54 vs. 50 mg/dL, IQE 40–62, p < 0.001) and higher hs-CRP levels (0.37 mg/dL, IQR 0.19–0.98 vs. 0.28 mg/dL IQE 0.13–0.67, p = 0.045) at baseline, as compared to patients without vitamin D deficiency." (PMID 40725860, 2025).
eosinophilia (137 papers, 2009 to 2026). "Moderate or severe eosinophilia is a risk factor for a significantly increased 3-month mortality, in patients older than 70 years with hematologic disease and an elevated C-reactive protein." (PMID 37274287, 2023). "For example, folic acid deficiency and severity of vaginal trichomoniasis were associated higher CRP, whereas eosinophilia, characteristic of intestinal nematode infections, was associated with lower CRP concentrations." (PMID 36079755, 2022). "Although, in general, WBC indices were within normal limits, we found eosinophilia, which is commonly associated with nematode infections, in 14.9% and elevated CRP in 12.1%." (PMID 33898918, 2021). "Immunoallergic liver injury mainly develops within 8 weeks after the initiation of DCV plus ASV therapy and is associated with eosinophilia and serum CRP elevation, while toxic liver injury occurs later than 8 weeks after the start of therapy." (PMID 30308053, 2018). "We have previously demonstrated presence of sustained inflammation in WTC dust exposed community members based on peripheral eosinophilia and increased C-reactive protein levels, findings that were associated with persistent abnormality in small airway function." (PMID 31009988, 2019). "In the future, we would like to examine the relationship between weekly CRP levels and the development of fever and eosinophilia, including asymptomatic patients." (PMID 39680690, 2026). "Laboratory findings showed elevated C-reactive protein, eosinophilia, and immunoglobulin E. Esophageal CT indicated localized wall edema, while infection was excluded." (PMID 42292807, 2026). "Baseline clinical disease activity was significantly higher than in the IBD-only controls, with concomitant elevations in biomarkers including monocytosis, eosinophilia, elevated C-reactive protein and elevated erythrocyte sedimentation rate." (PMID 42071861, 2026). "Additional laboratory abnormalities included eosinophilia, proteinuria, urinary tract infections, elevated C-reactive protein, neutrophilic leukocytosis, and hypercholesterolemia, consistent with systemic immune activation and renal involvement." (PMID 41446836, 2025). "Among biomarkers that have emerged as predictors of irAEs include eosinophilia, CRP, NLR, PLR, and ALC." (PMID 41235221, 2025). "Prior to the fifth dose, bowel movements had decreased to 3–5 loose stools per day, and abdominal pain had resolved, but hemoglobin dropped 6.8 g/dL, eosinophilia persisted, and platelet count rose to 521 × 103/μL; CRP was within normal limits." (PMID 41011540, 2025). "Laboratory findings included elevated serum creatinine (median 3.4 mg/dL, range: 1.6, 10.4), eosinophilia (18.5%), proteinuria (14.8%), urinary tract infection (11.1%), increased C-reactive protein (7.4%), and neutrophilic leukocytosis (3.7%)." (PMID 41446836, 2025). "Laboratory tests usually demonstrate transient peripheral eosinophilia, elevated acute phase reactants such as C-reactive protein, and hypergammaglobulinemia." (PMID 40099169, 2025). "Regarding the laboratory tests, high CRP levels and leucocytosis were observed in 28.6% of cases, eosinophilia in 9.5%, and PCT was always normal." (PMID 40898255, 2025). "Eosinophilia was noted in 18.5% of patients, proteinuria in 14.8%, urinary tract infection in 11.1%, while elevated C-reactive protein, neutrophilic leukocytosis, hypercholesterolemia, and hypercalcemia were reported in isolated cases." (PMID 41446836, 2025). "His initial workup showed an elevated white blood cell count with eosinophilia, a normal neutrophilic count, and an elevated C-reactive protein." (PMID 40041650, 2025). "Eosinophilia (20–25% of cases), abnormal urinalysis (pyuria, proteinuria, and hematuria), and elevated CRP have been observed in ATIN patients." (PMID 40000970, 2025).